CD14 (CD14 molecule)
Diseases named in the same sentence as CD14 in open-access papers (continued):
Sharing a sentence is not in itself a finding about the gene and the disease.
acute liver failure (3 papers, 2014 to 2020). Rapid deterioration of liver function causing encephalopathy and coagulopathy. "In addition, CD14+HLA-DR+MERTK+ cells were abundant in the circulation and the liver in acute liver failure where they were characterised as resolution-type monocytes/macrophages." (PMID 31822557, 2020). "In this study, we found a significantly reduced frequency of peripheral blood HLA-DR + CD14+ and Tim-3 + CD14+ monocytes in patients with H7N9 avian influenza, at levels similar to those in patients with septic shock, trauma and acute liver failure, as well as postoperative patients." (PMID 25030090, 2014).
acute pancreatitis (3 papers, 2018 to 2022). An acute inflammatory process that leads to necrosis of the pancreatic parenchyma. "The percentage of CD4+ lymphocytes expressing PD-1 and CD14+ monocytes expressing PD-L1 on day 1 and day 3 was higher in acute pancreatitis patients compared to healthy controls and higher in the IC group of acute pancreatitis patients compared to non-IC." (PMID 36010357, 2022).
alcohol abuse (3 papers, 2021 to 2023). The use of alcoholic beverages to excess, either on individual occasions ("binge drinking") or as a regular practice. "Given that CD14+CD16− monocytes were the main cell subset for which numbers were affected by alcohol abuse, we examined the functional profile of these cells." (PMID 34211048, 2021). "Regarding miRNA analysis of isolated CD14+ circulating monocytes, it is difficult to compare our data with those of other studies, owing to methodological differences and the fact that similar studies in the field of alcohol use disorders in humans have been performed in other tissues or plasma." (PMID 37760011, 2023).
alcoholic cirrhosis (3 papers, 2014 to 2023). "have shown association of this CD14 rs2569190 SNP with alcoholic cirrhosis in male from Rome, Italy and T allele frequency was higher in alcoholics (0.58) than non-alcoholic control (0.48)." (PMID 36238273, 2022). "We previously developed a prognostic model of future development of alcoholic cirrhosis in males that took into account BMI and the PNPLA3 rs738409 and cluster of differentiation 14 (CD14) rs2569190 variants." (PMID 37626629, 2023).
alcoholic hepatitis (3 papers, 2017 to 2019). Acute hepatitis resulting from ingestion of alcohol. "Monocytes were identified from blood samples of 42 patients with severe alcoholic hepatitis using monoclonal antibody to CD14." (PMID 26860769, 2017).
arteritis (3 papers, 2012 to 2025). An inflammatory process affecting an artery. "The number of helper T (Th), follicular helper T (Tfh), CD8+ T, CD14++ CD16+ monocytes, and neutrophils were higher in patients with giant cell arteritis (GCA) and/or Takayasu arteritis (TAK) than in HCs." (PMID 31888748, 2019). "Since the importance of TLR2 in LCWE-mediated arteritis, the aim of our study was to assess the involvement of TLR2 on CD14+ monocytes in both human KD and LCWE-induced arteritis mice, and to further validate the translational application of this mouse model for investigating human KD." (PMID 22737215, 2012). "In addition, the LCWE-induced arteritis mouse model is feasible for studying the immunopathogenesis of coronary arteritis in human KD and for determining methods for the prevention of coronary arteritis in human KD by blocking TLR2-mediated immune activation on CD14+ monocytes." (PMID 22737215, 2012).
atopic dermatitis (3 papers, 2014 to 2023). "According to a study conducted on a Ukrainian population, the carriers of the C allele at the polymorphic region C-159T of the CD14 gene were at increased risk of atopic dermatitis compared with carriers of the T allele." (PMID 37286630, 2023). "Combined effects of IL-13 or CD14 genetic variations and delivery mode on the development of atopic dermatitis (AD) at 1 year of age." (PMID 24848505, 2014).
atrial fibrillation (3 papers, 2017 to 2024). A disorder characterized by an electrocardiographic finding of a supraventricular arrhythmia characterized by the replacement of consistent P waves by rapid oscillations or fibrillatory waves that vary in size, shape and timing and are accompanied by an irregular ventricular response. "Similarly, CD14++CD16+ monocytes are increased in patients with atrial fibrillations and are considered to promote fibrotic remodeling of the atria through increased expression of TGFβ." (PMID 39273110, 2024).
bronchiolitis (3 papers, 2013 to 2019). Inflammation of the bronchioles characterized by swelling of the bronchioles and mucus accumulation. "This study found that CD14 (−550 C/T) is associated with higher serum levels of soluble (s) CD14 in Japanese neonates and children and directly correlates with development of bronchiolitis upon RSV infection." (PMID 31572372, 2019). "In infants with the TC + CC genotype of CD14, high levels of perinatal anxiety were associated with an increased risk of upper RTI, lower RTI, and bronchiolitis (aOR 2.51, 4.60, and 4.31, respectively)." (PMID 25263840, 2014). "CD14 serum levels in infants without recurrent wheezing was significantly higher than in wheezing infants, twelve months after hospitalization due to RSV-induced bronchiolitis." (PMID 23496969, 2013).
Cerebral ischemia (3 papers, 2013 to 2022). Restriction of arterial blood supply to the brain associated with insufficient oxygenation to support the metabolic requirements of the tissue. "The most significant enrichment in both study groups are for miRNAs expressed in immune cells harboring CD14, a receptor shown to mediate neuroinflammation induced by Alzheimer’s amyloid β peptides and cerebral ischemia in a mouse model." (PMID 35392269, 2022). "Collectively, the CD14 dimCD16+ non-classical Mo subset appears to be more closely associated with inflammation induced by infection as compared to that related to cerebral ischemia." (PMID 23936327, 2013). "Progression and severity of brain ischemia directly correlate with CD14++ CD16− increase and CD14+ CD16++ reduction." (PMID 27898011, 2016).
cerebral malaria (3 papers, 2009 to 2025). A sequestration of Plasmodium falciparum in the brain, which can cause coma and/or seizures. "CD14 was the only statistically significant association with cerebral malaria in both proteomic and transcriptomic analyses." (PMID 40383794, 2025). "The five identified proteins (ANK1, CD14, CDK14, ELANE, MPP1) were found to be elevated in the febrile convulsion group compared to cerebral malaria." (PMID 30442134, 2018).
chlamydial infection (3 papers, 2006 to 2020). "The number of CD14+ monocytes per 10 000 events was found to be significantly increased in women with chlamydial infections compared to controls (324 versus 312 and 147; P < 0.05 for fertile women, women with fertility disorders and controls respectively)." (PMID 18828896, 2008).
chronic obstructive pulmonary disease (3 papers, 2018 to 2022). A chronic and progressive lung disorder characterized by the loss of elasticity of the bronchial tree and the air sacs, destruction of the air sacs wall, thickening of the bronchial wall, and mucous accumulation in the bronchial tree. "The cytometric analysis of cell population isolated from patients with chronic obstructive pulmonary disease (COPD) has demonstrated that inhaled corticosteroids increase the expression of Siglec-5/14 in CD14+ cells." (PMID 32854433, 2020). "Recent studies have indicated that CD14+ BAL EV may be a potential biomarker for disease activity in chronic obstructive pulmonary disease (COPD)." (PMID 35234046, 2022). "In humans, high numbers of CD11b+CD14+CD16−HLA-DR− NO-producing myeloid-derived regulatory cells, which are phenotypically similar to MDSCs, were found in the airways of patients with asthma but not in patients with chronic obstructive pulmonary disease (COPD) or in healthy control subjects." (PMID 30237829, 2018).
chronic pancreatitis (3 papers, 2014 to 2025). A chronic inflammatory process causing damage and fibrosis of the pancreatic parenchyma. "To challenge the potential of EV markers CD14, GPC4, ANXA11, and CD44v6 in detecting PDAC patients, we analyzed their levels in a larger cohort of patients with PDAC and underlying pancreatic diseases: chronic pancreatitis and intraductal papillary mucinous neoplasm (IPMN)." (PMID 32990680, 2020).
colorectal adenocarcinoma (3 papers, 2016 to 2021). The most common type of colorectal carcinoma. "A higher number of cells expressing IL-2Rα, PD-L1, CD33 and CD14 were found in colorectal adenocarcinomas than in controls." (PMID 33625532, 2021). "As the activity of enhancers is known to be cell type-specific, we assayed chromatin interactions in monocytes (i.e. CD14+ fraction of PBMCs), lymphocytes (i.e. CD14- fraction of PBMCs), and in an intestinal epithelial cell line (DLD-1, derived from colorectal adenocarcinoma)." (PMID 27903283, 2016).
cystic fibrosis (3 papers, 2005 to 2021). Autosomal recessive disorder caused by pathogenic variants in the CFTR gene (cystic fibrosis transmembrane conductance regulator), which encodes a chloride and bicarbonate channel expressed in epithelial cells, and follow the diagnosis criteria. "The soluble form of CD14 has been used as a biomarker to predict pulmonary exacerbation in cystic fibrosis, and is increased in patients with chronic hepatitis." (PMID 32269570, 2020). "CD14+ monocytes were isolated from males and females with (n = 12) and without cystic fibrosis (n = 12) and examined for the expression of X-linked microRNAs by qRT-PCR array." (PMID 34868211, 2021).
dental caries (3 papers, 2017 to 2024). The decay of a tooth, in which it becomes softened, discolored, and/or porous. "In view of this, we aimed to evaluate the association between salivary CD14 and dental caries experience." (PMID 28936284, 2017). "This study aimed to evaluate the association of salivary soluble CD14 and dental caries in young children." (PMID 28936284, 2017). "Results obtained in our study suggested that salivary CD14 can be a indicator of dental caries in young children." (PMID 28936284, 2017). "In our study, an inverse relationship between dental caries and soluble salivary CD14 concentration was observed which was in accordance with previous study which used western blot method." (PMID 28936284, 2017). "Based on the results of the study, it can be concluded that salivary CD14 can be used as indicator of dental caries." (PMID 28936284, 2017). "The main purpose of the present study was to evaluate whether the salivary content of soluble CD14 was different between subjects with active dental caries or without carious lesions." (PMID 34438570, 2021).
eczema (3 papers, 2019 to 2025). "Another article showed that genetic background, such as CD14 polymorphisms, also affects the association between endotoxin concentration and developing eczema and FA." (PMID 36839328, 2023). "While in Pso a monocyte-derived DC (CD14+CD1a+CD11c+) predominated, possibly a Langerhans cell (LC)-like DC, eczema displayed a marker combination of a seemingly more differentiated monocyte-derived DC (CD14+CD63+CD163+), potentially a DC3 cell type." (PMID 41009640, 2025). "In summary, the presence of CD14+ cells, and to some degree CD1a+ cells, seemed characteristic for eczema compared with Pso." (PMID 41009640, 2025). "In Pso, almost all CD14+ cells were located in the dermis (dermis vs. epidermis: 92% vs. 8%), whereas in eczema a larger proportion was found in the epidermis (dermis vs. epidermis: 80% vs. 20%)." (PMID 41009640, 2025). "Since numbers of CD1a+ and CD14+ cells revealed notable differences in Pso and eczema, we decided to characterise these cells in more detail by including additional markers." (PMID 41009640, 2025). "There was a trend towards higher numbers in eczema compared with Pso, particularly in CD14+ cells." (PMID 41009640, 2025). "In addition, CD14+ cells were prominent in both the dermis and the epidermis of eczema." (PMID 41009640, 2025). "While Pso cells with DC markers maintained a CD14+, potentially LC-like phenotype (CD14+CD1a+CD11c+), cells in eczema displayed a marker combination that included CD163 and/or CD63, hinting at a more differentiated DC that may constitute a DC3 subtype, as previously suggested." (PMID 41009640, 2025). "For eczema and Pso, the appearance of CD63 and/or CD163 in combination with CD14 and/or CD1a and/or CD11c in eczema was most discriminatory." (PMID 41009640, 2025). "Supporting this conclusion, the marker combinations CD11c, CD63, CD163 and CD14, CD63, CD163 were almost exclusively found in eczema." (PMID 41009640, 2025). "For example, the marker combination CD14, CD63, and CD163 was 4.4-fold higher in eczema compared with Pso (~35 cells/mm2 vs. ~8 cells/mm2), and the marker combination CD11c, CD63, and CD163 was 8.4 fold higher (~25 cells/mm2 vs. 3 cells/mm2) (blue box)." (PMID 41009640, 2025). "In summary, CD14+ positive cells harbouring DC markers (CD11c, CD1a) in combination with CD63 and/or CD163 were far more present in eczema compared with Pso." (PMID 41009640, 2025). "In summary, the appearance of CD63 and/or CD163 on CD14+ and/or CD1a/CD11c+ cells were most characteristic and distinctive for eczema skin, whereas the same cells were lacking CD63/CD163 in psoriatic skin." (PMID 41009640, 2025).
encephalitis (3 papers, 2021 to 2025). An acute inflammatory process affecting the brain parenchyma. "Studies in an animal model of HIV neuropathogenesis have demonstrated the role of osteopontin (SPP1) in the recruitment and accumulation of monocytes in the CNS, while elevated expression of the osteopontin receptor on CD14+CD16hi monocytes was also linked to encephalitis." (PMID 40051633, 2025).
endometritis (3 papers, 2017 to 2025). An acute or chronic, usually bacterial infectious process affecting the endometrium. "Endometritis is characterized by the high expression of CD14, TLR4, IL-1α, IL1-β, IL-6, IL-8, and TNF-α in uterine tissue and cervical mucus." (PMID 39858163, 2025). "In addition, MC integration into local clusters of CD14+ cells became noticeable in severe endometritis." (PMID 41511322, 2025). "Higher counts of circulating CD14-negative monocytes prior to calving reduced the probability of postpartal infectious mastitis and/or endometritis, whereas an increase in CD14-positive monocyte counts prior to calving increased the susceptibility to infectious diseases postpartum." (PMID 29312348, 2017).
follicular lymphoma (3 papers, 2019 to 2024). Follicular lymphoma is a form of non-Hodgkin lymphoma characterized by a proliferation of B cells whose nodular structure of follicular architecture is preserved. "CD14+ FDCs are associated with poor prognosis in follicular lymphoma." (PMID 38301653, 2024). "Using biopsy specimens from follicular lymphoma (FL), we identified three subsets (CD14+SIRPαhi, CD14−SIRPαlow, and CD14−SIRPαneg) of monocyte/macrophages (Mo/MΦ) based on CD14 and SIRPα expression." (PMID 31611550, 2019). "Furthermore, a study in follicular lymphoma revealed that CD14+SIRPαhi cells phagocytosed tumor cells more efficiently and suppressed T-cell function in vitro compared with CD14+ SIRPαlow cells." (PMID 39696410, 2024).
gestational diabetes (3 papers, 2017 to 2023). Carbohydrate intolerance first diagnosed during pregnancy. "Decreased percentages of CD14+ CMs and increased abundances of IMs have also been observed in gestational diabetes mellitus, in which a hormone (human chorionic gonadotropin) made by the placenta prevents the body from using insulin effectively." (PMID 36921085, 2023). "In addition, we also used CD14++CD16− monocytes isolated from T2DM patients and human fetoplacental endothelial cells (HPEC) isolated from gestational diabetes patients." (PMID 36835891, 2023).
graft versus host disease (3 papers, 2018 to 2025). An immune system disorder that occurs after allogeneic hematopoietic stem cell transplant and is a reaction of donor immune cells against host tissues. "However, CD14+CD34+ also contribute to hepatic sinusoidal dilatation and immune cell infiltration, which may culminate in a graft-versus-host disease (GVHD) pathology upon long-term engraftment." (PMID 38853275, 2024).
hantavirus infection (3 papers, 2014 to 2020). "HTNV-Infected CD14+ monocytes, however, showed hantaviral N protein in patterns of small threads and inclusions typical of productive hantavirus infection." (PMID 32596167, 2020). "This suggests that the sCD163 that is shed during Hantavirus infection is likely from CD14++CD16+ monocytes." (PMID 25392926, 2014).
hemophagocytic syndrome (3 papers, 2014 to 2022). "Furthermore, in cases of increased presepsin levels in hemophagocytic syndrome, we speculated that phagocytes phagocytose CD14-expressing blood cells, resulting in increased presepsin levels." (PMID 35396366, 2022).
joint disease (3 papers, 2016 to 2021). "This study revealed that, in the IFP of arthropathy patients, abundant CD14-positive cell stores and the ratio of CD14++CD80+ cells/CD14++CD163+ cells were elevated, implying the localization of inflammation in the IFP." (PMID 34899727, 2021). "The quantity and quality of CD14-positive cells differed between IFP and SC in arthropathy patients." (PMID 34899727, 2021). "Of note, CD14− CD16+ mononuclear cells were completely absent from AS SF, indicating that they do not act locally to drive peripheral joint disease in AS." (PMID 26320138, 2016).
juvenile dermatomyositis (3 papers, 2023 to 2025). Juvenile dermatomyositis (JDM) is the early-onset form of dermatomyositis (DM), a systemic, autoimmune inflammatory muscle disorder, characterized by proximal muscle weakness, evocative skin lesion, and systemic manifestations. "In juvenile dermatomyositis (JDM), mitochondrial abnormalities in CD14+ monocytes, including the presence of “megamitochondria” and enhanced oxidative phosphorylation, promote the production of oxidized mitochondrial DNA." (PMID 40181992, 2025). "An innate immune signature was also unveiled when comparing JDM (juvenile dermatomyositis) skin biopsies to cutaneous lupus, (CLE), with an elevated expression of CD68+ and CD14+ macrophages." (PMID 39896815, 2024).
kidney damage (3 papers, 2017 to 2025). "The protective effect of CD14 neutralizing antibody treatment on LPS/Stx2-induced mouse kidney damage was validated by PAS (top) and H&E (bottom) staining." (PMID 39871175, 2025). "Notably, CD64 on CD14- CD16- monocytes was also associated with ARF (OR = 1.150, 95% CI = 1.027–1.289, p = 0.016), indicating a potential link between monocyte activation and kidney damage." (PMID 41844385, 2025).
leishmaniasis (3 papers, 2018 to 2020). Infectious disease that is transmitted through the bite of hematophagous female phlebotomine sand flies. "In this paper, the downstream gene network of CD14-TNF-EGFR pathway in leishmaniasis, a tropical disease, is reconstructed." (PMID 29472639, 2018). "Furthermore, expression of IFNA1 and IFNB1 was highest in CD1c+ DCs relative to B cells (CD19+) and monocytes (CD14+), other likely cellular sources of these cytokines in experimental leishmaniasis." (PMID 32101732, 2020).
leukopenia (3 papers, 2015 to 2023). "Taken together, these observations indicate rapid leukopenia after the onset of LPS infusion, which was followed by an increase in the polymorphonuclear cells and expansion of the CD14+CD163+ monocytes, especially in the control animals." (PMID 35566768, 2022).
lymph node metastasis (3 papers, 2019 to 2022). "MGL ligand expression was also associated with lymph node metastasis, the absence of CD14+ myeloid cells and the presence of CD14−CD163+ myeloid cells." (PMID 30761272, 2019).